PSAT1 (phosphoserine aminotransferase 1)
Diseases named in the same sentence as PSAT1 in open-access papers (continued):
Sharing a sentence is not in itself a finding about the gene and the disease.
Neu-Laxova syndrome (5 papers, 2020 to 2025). Neu-Laxova syndrome (NLS) is a rare, multiple malformation syndrome characterized by severe intrauterine growth retardation (IUGR), severe microcephaly with a sloping forehead, severe ichthyosis (collodion baby type), and facial dysmorphism. "It was shown that homozygous mutation in PSAT1 causes death before weaning in mice, and mutations also result in Neu-Laxova syndrome and phosphoserine aminotransferase deficiency 68-70." (PMID 40756345, 2025). "The PSAT1 gene has been described in the scientific literature as the cause, among other phenotypes, of Neu Laxova 2 syndrome, with an autosomal recessive model of inheritance." (PMID 35885441, 2022). "Mutations PHGDH, PSPH, and PSAT1 in the serine-glycine pathway have been associated with Neu-Laxova syndrome, which is characterized by a spectrum of phenotypes that vary in expression but usually manifests by perinatal lethality, microcephaly, skeletal, and skin anomalies." (PMID 36737727, 2023). "Genetic deficiency in the de novo serine biosynthesis genes PHGDH, PSAT1, and PSPH, in humans causes Neu-Laxova syndrome (NLS), a very rare autosomal recessive congenital disorder." (PMID 32549981, 2020).
Burkitt lymphoma (4 papers, 2020 to 2024). A rare form of malignant mature B-cell non-Hodgkin lymphoma. "Burkitt lymphomas, highly proliferative and metabolically demanding tumors, overexpress serine biosynthesis pathway (SBP) enzymes, phosphoglycerate dehydrogenase (PHGDH), and phosphoserine aminotransferase 1 (PSAT1)." (PMID 32138178, 2020).
osteosarcoma (4 papers, 2020 to 2025). A usually aggressive malignant bone-forming mesenchymal neoplasm, predominantly affecting adolescents and young adults. "Down regulation of HSPA5 can promote ANXA1 and repress PSAT1 expression, which inhibiting the osteosarcoma cell proliferation and inducing cell apoptosis." (PMID 34412642, 2021). "Suppression of HSPA5 effectively upregulated ANXA1 and inhibited PSAT1, resulting in osteosarcoma cell proliferation arrest and apoptosis." (PMID 33291071, 2020). "Two candidate biomarkers, ANXA1 and PSAT1, for the prognosis of osteosarcoma were detected separately on the basis of WGCNA and LASSO model." (PMID 33291071, 2020). "To study the intracellular localization of PSAT1, we used indirect immunofluorescence to evaluate the distribution of PSAT1 in the endoplasmic reticulum (ER), nucleus and microtubules of A-431 (Human epidermal carcinoma), U-251MG (Human astroglioma cells) and U-2 osteosarcoma cells." (PMID 36105075, 2022).
thyroid cancer (4 papers, 2019 to 2024). "Glutamine metabolism-related genes, including amino acid transporter (ASCT2), amino-releasing enzymes (GLS and GDH), and aminotransferases (GPT, GOT, and PSAT1), were all up-regulated in thyroid cancer cells." (PMID 38386265, 2024). "PSAT1 expression differs significantly in BRCA, KIRC, Kidney Chromophobe (KICH), KIRP, STAD, TGCT, thyroid carcinoma (THCA) and UCEC in different stages, but it is particularly pronounced in KIRP." (PMID 36105075, 2022). "Other glutamine metabolism-related genes, such as solute carrier family 1 neutral amino acid transporter member 5 (SLC1A5, also known as ASCT2), phosphoserine aminotransferase 1 (PAST1), GPT, and glutamic-oxaloacetic transaminase (GOT), were also highly expressed in thyroid cancer cells." (PMID 38386265, 2024).
viral infections (4 papers, 2020 to 2025). "Viral infections are known to increase PHGDH and PSAT1 expression, but how they impact pulmonary functions remains unclear." (PMID 40262853, 2025). "PSAT1 and ACTA2 were up-regulated in response to all viral infections, with higher induction in cells infected with CHIKV and MAYV at 18 hpi." (PMID 33791243, 2021).
cervical cancer (3 papers, 2023 to 2024). A primary or metastatic malignant neoplasm involving the cervix. "Furthermore, it is noteworthy that PSAT1 has been documented to stimulate cell proliferation while inhibiting apoptosis through the activation of the PI3K/AKT signaling pathway, thereby imparting increased resistance to cisplatin in cervical cancer cells." (PMID 38706897, 2024).
diabetes (3 papers, 2018 to 2021). "Expression of phosphoserine aminotransferase 1, which is involved in the synthesis of serine, is reduced in mice with diabetes induced by a high-fat diet." (PMID 34071816, 2021). "We identified key genes (GYS1, PYGL, and PSAT1) from both pathways that have previously been demonstrated to play a role in glucose tolerance/ insulin sensitivity in models of obesity and diabetes and epidemiological studies." (PMID 30483256, 2018).
endometrial cancer (3 papers, 2018 to 2025). Primary or metastatic malignant neoplasm involving the endometrium (mucous membrane that lines the endometrial cavity). "Subsequent transfection experiment of a miR mimic/inhibitor showed that PSAT1 was negatively regulated by miR-195-5P, whereas miR-497-5P had no significant regulatory effect on Ishikawa or HEC-1-A cells—human endometrial cancer cell lines." (PMID 36906716, 2023). "Survival analysis showed that the higher the expression levels of lncRNAs C2orf48, PSAT1, KIF23, CCNE1, CDC25A and CBX2 in patients with endometrial cancer, the poorer the prognosis." (PMID 30581678, 2018).
lymph node metastasis (3 papers, 2015 to 2025). "Patients exhibiting high PSAT1 and SLC1A5 expression were more likely to develop lymph node metastasis, while high PHGDH, PSPH and SLC1A5 expression were associated with distant metastasis." (PMID 40660426, 2025).
Obesity (3 papers, 2018 to 2022). Accumulation of substantial excess body fat. "From a physiological perspective focusing on obesity and its related metabolic diseases, hepatic PSAT1 has revealed a novel function in the regulation of insulin sensitivity." (PMID 31234367, 2019). "Lactobacillus rhamnosus hsryfm 1301 fermented milk inhibited transcription of Psat1 and Phgdh by increasing the levels of L-Threonine, L-Serine and glyceric acid, which, in turn, regulated the amino acid metabolic pathways and alleviated onset and development of obesity." (PMID 36432537, 2022).
pancreatic cancer (3 papers, 2021 to 2022). "PSAT1 regulation has been shown to be important in other tumor types, including in pancreatic cancer, in which modulation of PSAT1 expression in LKB1-mutant tumors influences epigenetics and gene expression." (PMID 35045283, 2022).
sarcoma (3 papers, 2015 to 2022). A usually aggressive malignant neoplasm of the soft tissue or bone. "Our further analysis found that for tumor patients with higher PSAT1 expression, such as ACC, KIRC, KIRP, LIHC, sarcoma (SARC) and UVM, the overexpression of PSAT1 is associated with poor OS." (PMID 36105075, 2022). "PSAT1 expression was up-regulated in sarcoma bone cancer tissues showing in ONCOMINE and GENT2 database." (PMID 33291071, 2020). "However, in our screen, silencing of PSAT1, PHGDH or BCAT1 did not inhibit sarcoma cell growth, suggesting that these biosynthetic pathways may be of lesser importance for the sarcomatous malignancies studied here." (PMID 26499495, 2015).
serine deficiency (3 papers, 2022 to 2025). "Our study expanded the clinical spectrum of PSAT1-related serine deficiency." (PMID 36061210, 2022).
gastric cancer (2 papers, 2022 to 2025). A primary or metastatic malignant neoplasm involving the stomach. "PSAT1 was highly expressed in gastric cancer, and its low expression was associated with a poor prognosis." (PMID 36061202, 2022). "Nine microRNAs targeting PSAT1 and associated with gastric cancer were screened by miRwalk and microRNA expression in TCGA tumor tissues." (PMID 36061202, 2022). "Furthermore, we identified miRNAs targeting PSAT1 in TCGA tumor tissues and associated them with gastric cancer." (PMID 36061202, 2022). "Furthermore, microRNAs targeting PSAT1 can predict gastric cancer prognosis and bone metastasis risk." (PMID 36061202, 2022). "Gastric cancers expressed high levels of PSAT1, and low levels were associated with poor prognoses." (PMID 36061202, 2022). "In gastric cancer, low expression of PSAT1 was associated with worse OS, DSS, and PFI." (PMID 36061202, 2022). "The relationship between the clinical manifestations of gastric cancer in patients and phosphoserine aminotransferase 1 (PSAT1) was analyzed using correlation analysis." (PMID 36061202, 2022). "MicroRNAs targeting the regulation of PSAT1 expression can well predict the prognosis of gastric cancer." (PMID 36061202, 2022). "PSAT1 expression was highly correlated with poor prognosis in gastric cancer in this study based on pan-cancer analysis." (PMID 36061202, 2022). "We screened the PSAT1-targeting microRNAs with miRWalk, and then analyzed their expression in gastric cancer." (PMID 36061202, 2022). "According to immune infiltration analysis, PSAT1 affects the tumor immune microenvironment, which indicates that PSAT1 plays a critical role in invasion and gastric cancer prognosis." (PMID 36061202, 2022). "In this study, we analyzed the clinical and tumor microenvironment of gastric cancer patients to investigate the relationship between PSAT1 and prognosis." (PMID 36061202, 2022). "This study analyzed PSAT1-targeted miRNAs as a prognostic predictor for gastric cancer." (PMID 36061202, 2022). "Gastric cancer patients’ demographic characteristics and PSAT1 expression." (PMID 36061202, 2022). "Therefore, patients with gastric cancer with low expression of PSAT1 had a poor prognosis." (PMID 36061202, 2022).
Insulin resistance (2 papers, 2019). Increased resistance towards insulin, that is, diminished effectiveness of insulin in reducing blood glucose levels. "The involvement of the nonessential amino acid serine in the regulation of insulin sensitivity opened lines of research into the targeting of PSAT1 for treatment of insulin resistance and type 2 diabetes in mice." (PMID 31234367, 2019). "Low expression of PSAT1 contributes to the progression of insulin resistance through the inactivation of insulin signaling." (PMID 30678306, 2019).
neuroblastoma (2 papers, 2022 to 2023). Neuroblastoma (NB) is the most common solid, extracranial childhood tumor. "MYCN can also drive transcription of ATF4 in neuroblastoma cells, and it was demostrated that targeting either MYCN or ATF4 leads to decreased expression levels of PHGDH, PSAT1, SHMT2, MTHFD2, and MTHFD1L." (PMID 37949226, 2023). "A Negative correlation between PSAT1 expression and most immunosuppressive and immunostimulatory agents was found in TGCT, Neuroblastoma (NB), KIPAN, LUSC and THCA." (PMID 36105075, 2022).
Phosphoserine aminotransferase deficiency (2 papers, 2021 to 2023). Phosphoserine aminotransferase deficiency is an extremely rare form of serine deficiency syndrome (see this term) characterized clinically in the two reported cases to date by acquired microcephaly, psychomotor retardation, intractable seizures and hypertonia. "Pathogenic variants in PSAT1 cause disease that ranges from severe (Neu-Laxova syndrome 2, NLS2 [MIM: 616038]) to milder forms (PSAT deficiency, PSATD [MIM: 610992])." (PMID 37812589, 2023). "This deletion encompasses the CEP78 and PSAT1 (MIM #610936) genes, the latter of which has so far only been implicated in recessive phosphoserine aminotransferase deficiency (MIM # 610992) and Neu-Laxova syndrome 2 (MIM # 616038)." (PMID 33968938, 2021).
pulmonary fibrosis (2 papers, 2022 to 2023). Chronic progressive interstitial lung disorder characterized by the replacement of the lung tissue by connective tissue, leading to progressive dyspnea, respiratory failure, or right heart failure. "By focusing on PSAT1 expression in vivo and in vitro, vitamin D3 regulates the MAPK pathway and reduces pulmonary fibrosis, as demonstrated by Wenxiang Zhu65." (PMID 36307516, 2022).
renal carcinoma (2 papers, 2021 to 2022). A carcinoma arising from the epithelium of the renal parenchyma or the renal pelvis. "The high expression of HK3, ENO2, ENO3, and PSAT1 indicated a short OS and a high risk of developing renal cancer." (PMID 33564363, 2021). "The high expression of GAPDH, PSAT1, PGLS, and LDHC indicated a short DFS and a high risk of developing renal cancer." (PMID 33564363, 2021). "Thus, this study selected IYD, ACADSB, and PSAT1 for validation since they had not been validated in renal cancer tissues and cell lines." (PMID 36118874, 2022).
uterine corpus endometrial carcinoma (2 papers, 2022 to 2023). A endometrial carcinoma (disease) that involves the body of uterus. "Phosphoserine aminotransferase 1 (PSAT1) has been associated with the occurrence and development of various carcinomas; however, its function in uterine corpus endometrial carcinoma (UCEC) is unknown." (PMID 36906716, 2023).
acute myeloid leukemia (1 paper, 2022). Acute myeloid leukemia (AML) is a group of neoplasms arising from precursor cells committed to the myeloid cell-line differentiation. "However, the expression of PSAT1 is lower in Acute Myeloid Leukemia (LAML), Cholangiocarcinoma (CHOL), Kidney renal clear cell carcinoma (KIRC), Kidney renal papillary cell carcinoma (KIRP) than the corresponding normal tissues." (PMID 36105075, 2022).
autonomic neuropathy (1 paper, 2022). An inherited or acquired peripheral neuropathy affecting the autonomic nervous system. "The neuropathy associated with SPTLC1 mutation exhibited some improvement after supplementation with oral L-serine, which also partially improved the symptoms of sensorimotor and autonomic neuropathy in our PSAT1-related patients." (PMID 36061210, 2022).
clear cell carcinoma (1 paper, 2024). "For example, in clinical practice, when the clinical renal cell carcinoma patients after surgical treatment, the histopathology suggests that the renal cell carcinoma is clear cell carcinoma, the expression of PSAT1 can be further detected by immunohistochemistry." (PMID 38614981, 2024).
diffuse large B-cell lymphoma (1 paper, 2020). "We first investigated the expression of SBP genes, PHGDH and PSAT1, in BL and another type of aggressive B-cell malignancy, diffuse large B-cell lymphoma (DLBCL), using a publicly available dataset." (PMID 32138178, 2020).
epilepsy (1 paper, 2025). A brain disorder characterized by episodes of abnormally increased neuronal discharge resulting in transient episodes of sensory or motor neurological dysfunction, or psychic dysfunction. "We also observed that epilepsy-associated genes PDCC10, PHGDH, PSAT1, and TBC1D24 showed higher expression levels in SOZ compared with PZ." (PMID 39541170, 2025).
follicular adenoma (1 paper, 2016). "Among follicular neoplasms, the expression of PSAT1 was higher in follicular adenoma compared to FC (24.2 versus 8.0 %, p = 0.001)." (PMID 27277113, 2016).
hepatoblastoma (1 paper, 2024). Hepatoblastoma (HB) is a malignant hepatic tumor and is the most common pediatric liver cancer. "Reduced LATS2 expression promotes hepatoblastoma progression by inhibiting ferroptosis through the YAP1/ATF4/PSAT1 axis." (PMID 39247829, 2024).
HIV-1 infection (1 paper, 2016). The type species of lentivirus and the etiologic agent of acquired immunodeficiency syndrome (AIDS). "The predicted models of PHGDH and PSAT1 interaction with other cellular gene products and pathways indicate a central role for these enzymes in helping the cell to adapt to metabolic changes in response to HIV-1 infection." (PMID 26821323, 2016).
ichthyosis (1 paper, 2022). Disorders of cornification that are characterized by visible scaling and/or hyperkeratosis of most or all of the skin. "Our patients presented with infancy- or childhood-onset ichthyosis and juvenile-onset peripheral neuropathy, which expands the clinical phenotype of PSAT1-related serine deficiency disorder." (PMID 36061210, 2022). "However, in adult individuals with serine deficiency disorder, only PSAT1-related patients presented with ichthyosis, but not in PHGDH- and PSPH-related patients." (PMID 36061210, 2022).
influenza infection (1 paper, 2023). "For example, SERPINB1 has been reported to influence the innate immune system during influenza infection, PTCH1 is important for macrophage chemotaxis during gastric inflammation, and PSAT1 regulates the inflammatory response in macrophages." (PMID 36761770, 2023).
ischemic heart diseases (1 paper, 2025). "Our findings identify PSAT1 as a pleiotropic regulator of cardiac repair and a promising candidate for mRNA-based therapies in ischemic heart disease." (PMID 40756345, 2025). "The clinical potential of PSAT1 modRNA for ischemic heart diseases is promising, offering benefits such as promoting cardiomyocyte proliferation, inhibiting oxidative stress and cell death, enhancing cardiac repair, and improving post-MI function." (PMID 40756345, 2025).
lymphoma (1 paper, 2022). A malignant (clonal) proliferation of B- lymphocytes or T- lymphocytes which involves the lymph nodes, bone marrow and/or extranodal sites. "Immunoblotting and IHC showed higher expression of PHGDH and PSAT1 in B cells from lymphoma-bearing Eμ-Myc heterozygote mice when compared with WT C57BL/6J syngenic mice." (PMID 35316216, 2022).
male infertility (1 paper, 2024). The inability of the male to effect fertilization of an ovum after a specified period of unprotected intercourse. "In humans, a PSAT1 SNP has been described, which was significantly associated with male infertility traits and might explain to some extent the genetic contribution to severe oligospermia." (PMID 38540441, 2024).
mesothelioma (1 paper, 2022). A usually malignant and aggressive neoplasm of the mesothelium which is often associated with exposure to asbestos. "However, it is rare to find PSAT1 in mesothelioma in previous studies." (PMID 36105075, 2022).
metastatic prostate carcinoma (1 paper, 2025). A carcinoma that arises from the prostate gland and has spread to other anatomic sites. "Notably, while PSAT1 and PSPH exhibited no change in expression by PLK1, PHGDH showed a significant decrease in our experimental models of advanced metastatic prostate cancers." (PMID 40475404, 2025).
myocardial infarction (1 paper, 2025). Gross necrosis of the myocardium, as a result of interruption of the blood supply to the area, as in coronary thrombosis. "Notably, an enhancement in capillary density post-myocardial infarction (MI) was observed following PSAT1 modRNA injection." (PMID 40756345, 2025).
neuropathy (1 paper, 2022). A disorder affecting the nervous system that manifests with pain, tingling, numbness, and/or muscle weakness. "Therefore, early diagnosis and treatment are vital to the prognosis of PSAT1-related neuropathy as a treatable disease." (PMID 36061210, 2022).
Nystagmus (1 paper, 2022). Rhythmic, involuntary oscillations of one or both eyes related to abnormality in fixation, conjugate gaze, or vestibular mechanisms. "Additionally, some patients with PSAT1 mutations showed sensorineural hearing loss and nystagmus that was usually attributed to dysfunctions of auditory and vestibular nerves or their ascending pathways." (PMID 36061210, 2022).
osteoarthritis (1 paper, 2024). A noninflammatory degenerative joint disease occurring chiefly in older persons, characterized by degeneration of the articular cartilage, hypertrophy of bone at the margins and changes in the synovial membrane. "For instance, curcumin may exhibit therapeutic effects on osteoarthritis by modulating the CBS, CTH, PSAT1, MAOA, and AOC2 proteins involved in the metabolism of glycine, serine, and threonine." (PMID 37938371, 2024). "Overall, we postulate that curcumin might have therapeutic potential in the management of osteoarthritis by targeting CBS, PSAT1, MAOA, and other crucial proteins." (PMID 37938371, 2024). "Moreover, curcumin may have therapeutic effects on osteoarthritis by interacting with the CTH, CBS, CDO1, and PSAT1 proteins involved in cysteine and methionine metabolism." (PMID 37938371, 2024).